METTL3 (methyltransferase 3, N6-adenosine-methyltransferase complex catalytic subunit)
Diseases named in the same sentence as METTL3 in open-access papers (continued):
Sharing a sentence is not in itself a finding about the gene and the disease.
breast cancer (continued). "In breast cancer, METTL3 directly targets BCL-2 by increasing the extent of the m6A modification of BCL-2 to increase its RNA and protein expression levels, thereby regulating the proliferation and apoptosis of breast cancer." (PMID 34315512, 2021). "METTL3 was also elevated in other solid tumors such as breast cancer, pancreatic cancer and promotes growth, invasion and drug resistance of cancer cells." (PMID 32111213, 2020). "For example, METTL3 promotes the progression of breast cancer by inhibiting tumor suppressor let-7 g." (PMID 32631107, 2020). "The expression of METTL3 in breast cancer tissues was lower than that in normal tissues, and METTL3 was a protective factor of DMFS in TNBC." (PMID 32766145, 2020). "In breast cancer, miRNA let-7 g downregulates METTL3 expression by targeting its mRNA 3′-UTR, while hepatitis B X-interacting protein (HBXIP) improves METTL3 expression by inhibiting the function of let-7 g." (PMID 32443966, 2020). "ZNF217, an m6A methyltransferase inhibitor targeting METTL3, is upregulated in hypoxia-induced breast cancer cells." (PMID 33162550, 2020). "For instance, the m6A writer protein METTL3 is a reported oncogene for liver cancer 44, bladder cancer 45 and acute myeloid leukemia 46, but a tumor suppressor for breast cancer." (PMID 32742465, 2020). "HBXIP can extensively elevate the expression of METTL3 and concurrently inhibit let-7g so as to promote breast cancer progression." (PMID 33048840, 2020). "In order to verify the effects of METTL3 and COL3A1 on the prognosis of breast cancer patients in vivo, the expression of METTL3 and COL3A1 was investigated by immunohistochemistry using TMA sections containing 31 TNBC patients and 109 Non-TNBC patients." (PMID 32766145, 2020). "Increase in m6A modification by METTL3 was shown to promote HBXIP expression which in turn rescued the miR let-7g-mediated METTL3 suppression in breast cancer cells." (PMID 32194861, 2020). "The function of METTL3 and other m6A modulators in other sub-types of breast cancer warrants further investigation in the future." (PMID 32766145, 2020). "And the last one claims that the up-regulated METTL3 contributes to breast cancer via targeting Bcl-2 mRNA and enhancing its translation." (PMID 32612834, 2020). "METTL3 was found to be upregulated in breast cancer tissues and cells, where it promoted m6A modification of the 3′ UTR of B-cell/lymphoma 2 (BCL-2) mRNA." (PMID 32398132, 2020). "In recent studies, high METTL3 levels were related to tumour invasion and poor outcomes in breast cancer and acute myeloid leukaemia (AML)." (PMID 33059689, 2020). "METTL3, the core component of MTC, enhances cell proliferation via a positive feedback loop of the HBXIP/let-7g/METTL3/HBXIP axis in breast cancer." (PMID 33292526, 2020). "For example, in CRC, SOX2 plays a cancer-promoting role through METTL3-catalyzed methylation, while in breast cancer, BNIP3 plays a cancer-promoting role through FTO-catalyzed demethylation." (PMID 32398132, 2020). "In breast cancer, the tumor-promoting activity of the m6A regulators such as METTL3 and ALKBH5 were also described." (PMID 33584787, 2020). "HBXIP-induced METTL3 promotes the proliferation of breast cancer via inhibiting tumor suppressor let-7 g." (PMID 31142332, 2019). "METTL3 is associated with the expression of mammalian hepatitis B X-interacting protein (HBXIP), displaying an aggressiveness in breast cancer." (PMID 31142332, 2019). "Expression of METTL3 has been also shown to be positively regulated by hepatitis B X-interacting protein (HBXIP) by downregulating the levels of let-7g during breast cancer progression." (PMID 31426393, 2019). "Hepatitis B X-interacting protein (HBXIP) upregulates METTL3 in breast cancer cells by inhibiting the miRNA let-7g, which downregulates the expression of METTL3 by targeting its 3′UTR." (PMID 31921660, 2019).
breast cancer (continued). "Knockdown of METTL3 reduced cell proliferation and accelerated apoptosis and migration by targeting Bcl-2, suggesting the oncogenic role of METTL3 in breast cancer." (PMID 31921660, 2019). "A study showed that hypoxia was related to increased breast cancer stem cell formation directly through upregulating ALKBH5 or indirectly through ZNF217/METTL3-METTL14-complex pathway." (PMID 30877265, 2019). "Interesting, either METTL3 overexpression or ALKBH5 depletion in breast cancer cells leads to suppression of cancerous phenotypes." (PMID 31426393, 2019). "This regulatory mechanism led to the formation of a positive feedback loop of HBXIP/let-7g/METTL3/HBXIP in breast cancer cells and promoted the occurrence, proliferation, and invasion of breast cancer cells." (PMID 31757221, 2019). "METTL14 expression is positively correlated with METTL3 expression and is highly expressed in breast cancer." (PMID 31808521, 2019). "There remains a coherent natural link between the oncoprotein hepatitis B virus X-interacting protein (HBXIP) and METTL3 in the development of breast cancer (BC)." (PMID 29587823, 2018). "Recently, it was discovered that the oncoprotein hepatitis B X-interacting protein (HBXIP), whose aberrant expression drives the aggressiveness of breast cancer, releases the expression of METTL3 by repressing its inhibitor let-7 g." (PMID 30149601, 2018). "Mechanistically, HBXIP upregulates METTL3 in breast cancer cells by inhibiting miRNA let-7g, which downregulates the expression of METTL3 by targeting its 3′UTR." (PMID 29587823, 2018). "Using this model of breast cancer development, we found that immortalization resulted in reduced m6A levels as well as significant down-regulation of the m6A methylation complex (METTL3/14) and up-regulation of the primary demethylase (ALKBH5)." (PMID 30131850, 2018). "According to certain research, PIN1 regulates the translation of mRNA, and the PIN1/METTL3 axis may serve as an alternative therapeutic target for breast cancer." (PMID 40919129, 2025). "Moreover, combined inhibition of METTL3/METTL14 with paclitaxel (PTX) demonstrated potent synergistic antitumor effects in breast cancer cells and xenograft models." (PMID 41164187, 2025). "Specifically, within Dox‐resistant breast cancer cells, the expression level of METTL3 is elevated." (PMID 39972939, 2025). "METTL3 maintains m6A methylation homeostasis by methylating target mRNA and is involved in a variety of pathological processes, including colorectal carcinoma, breast cancer, chronic obstructive pulmonary disease, and DR." (PMID 40727611, 2025). "Furthermore, METTL3 has been found to interact with the transactivation domain of EGF-induced STAT5B in the nucleus of breast cancer cells." (PMID 40507264, 2025). "Interestingly, early-stage breast cancer cells exhibited enhanced proliferative capacity upon METTL3 silencing, while malignant transformed counterparts displayed increased migratory potential." (PMID 40986143, 2025). "Notably, METTL3 downregulation exerted minimal phenotypic impact on metastatic breast cancer cell lines." (PMID 40986143, 2025). "Recent studies have highlighted ZNF217's role in modulating m6A RNA methylation, showcasing its diverse mechanisms of action, from blocking the m6A "writer" METTL3 in embryonic stem cells and breast cancer cells to enhancing the transcription of the m6A "eraser" FTO in adipocytes 40-45." (PMID 40093906, 2025). "Specifically, METTL3 association with the CCND1 (cyclin D1) promoter region was reduced with STAT5B knockdown, but not STAT5A, which impaired cell cycle progression in hormone receptor-positive MCF7 breast cancer cells." (PMID 40507264, 2025). "BBR could also blocked breast cancer cell growth and metastasis partly by regulating METTL3-mediated m6A modification of FGF7 Mrna." (PMID 40829428, 2025). "A wealth of studies has demonstrated that METTL3 is upregulated in breast cancer cells." (PMID 39972939, 2025).
breast cancer (continued). "In breast cancer, the expression of METTL3 is significantly upregulated." (PMID 40919129, 2025). "In contrast to previous findings where cytoplasmic METTL3 displayed an oncogenic role, this investigation reveals a strong correlation between nuclear METTL3 levels and node breast cancer metastasis, being the cytoplasmic expression restricted to normal and non-invasive tissues." (PMID 38444581, 2024). "Conversely, within the context of breast cancer, the m6A modification catalyzed by METTL3 not only bolsters the longevity of PD-L1 mRNA transcripts but also facilitates their transcriptional activation, a process that hinges on the recognition of the m6A mark by the IGF2BP3 protein." (PMID 39372415, 2024). "Importantly, knocking out METTL3/METTL14 sensitizes breast cancer cells to ER stress-inducing drugs." (PMID 39085650, 2024). "To determine whether these bands were derived from METTL3, we constructed METTL3 knockdown in human T47D breast cancer cell lines by METTL3 shRNA and found that the amount of these two short bands was abolished." (PMID 37589705, 2023). "Additionally, our RNA-seq data showed that genes involved in proliferation and migration, including cell-cell adhesion, were altered upon depletion of METTL3 in breast cancer cell lines." (PMID 36725888, 2023). "METTL3 increased PD-L1 mRNA levels in an m6A-IGF2BP3-dependent manner in breast cancer cells." (PMID 36835633, 2023). "Therefore, metformin/miR‐483‐3p alleviated METTL3's oncogenic effect, promoting anti‐proliferation activity in breast cancer." (PMID 36162823, 2023). "Notably, we found that deletion of METTL3 decreased glycolytic activity in breast cancer cell lines." (PMID 36609396, 2023). "Sulfation plays an important role in the anti-tumorigenic mechanism of tamoxifen, suggesting that METTL3 could increase the sensibility of hormone therapy in the luminal A breast cancer subtype." (PMID 36725888, 2023). "This suggests that PIN1 regulates METTL3 through ubiquitination in breast cancer." (PMID 37391814, 2023). "Additionally, pathway enrichment analysis of the differentially expressed genes indicated that METTL3 was significantly related to breast cancer and the Hippo pathway." (PMID 36609396, 2023). "In breast cancer, metformin exerted an anti‐growth effect via reinforcing miR‐483‐3p level, which could silence oncogenic METTL3 and restore apoptosis‐related p21." (PMID 36162823, 2023). "In addition, the protein levels of METTL3 were inversely correlated with the mRNA levels of LATS1 in breast cancer cells." (PMID 36609396, 2023). "Moreover, the seahorse assay revealed that glycolysis was upregulated when LATS1 expression was suppressed after METTL3 expression was deleted in breast cancer cells." (PMID 36609396, 2023). "We also investigated global changes in the transcriptome resulting from Mettl3 knock down in our breast cancer model to identify pathways that may be regulating the phenotypic changes observed." (PMID 38023205, 2023). "Adenosine deaminase acting on RNA 1 (ADAR1) and METTL3 were upregulated in breast cancer samples." (PMID 36835633, 2023). "METTL3 mediates the overexpression of MALAT1 in adriamycin resistant breast cancer through m6A." (PMID 37901333, 2023). "To further explore whether METTL3 decreases resistance to DOX in breast cancer, we treated mice with PBS and DOX." (PMID 36765397, 2023). "METTL3 is highly expressed during breast cancer metastasis, demonstrating that METTL3 plays an oncogenic role in breast cancer and may be a potential therapeutic target." (PMID 39872957, 2023). "METTL3 could enhance the m6A methylation of pri-miR-221-3p, thereby increasing the expression of miR-221-3p and increase the drug resistance of breast cancer cells through the miR-221-3p/HIPK2/Che-1 axis." (PMID 37901333, 2023). "Overall, these results suggest that METTL3 may indirectly regulate AS in breast cancer via m6A deposition in MYC mRNA." (PMID 36725888, 2023).
breast cancer (continued). "We also interrogated genome-wide METTL3-regulated AS events in breast cancer cell lines." (PMID 36725888, 2023). "Notably, high expression of METTL3 and MALAT1 in breast cancer has been associated with poor prognosis." (PMID 37369946, 2023). "Based on these data, we confirmed the important role of METTL3 in breast cancer tumorigenesis." (PMID 36609396, 2023). "METTL3/miR-221-3p/HIPK2/Che-1 axis as a novel signaling pathway that may be responsible for breast cancer resistance to adriamycin." (PMID 39872957, 2023). "METTL3 functions as an immunomodulator in the breast cancer microenvironment." (PMID 39872957, 2023). "Since RNA-seq revealed that METTL3 might be related to glycolysis in breast tumor cells, we conducted metabolomic-seq analysis in METTL3 KO MCF-7 breast cancer cells." (PMID 36609396, 2023). "In breast cancer cells, METTL3 mediates methylation of the lncRNA MALAT1 that promotes metastasis." (PMID 37369946, 2023). "Taken together, these results suggest that METTL3 promotes breast cancer growth." (PMID 36725888, 2023). "METTL3 downregulation induced the destabilization of PD-L1 mRNA in breast cancer cells." (PMID 36835633, 2023). "Since METTL3 is an important m6A writer, we further examined whether METTL3 exerted regulatory effects on the overall m6A modification in the breast cancer cells." (PMID 35197058, 2022). "Altogether, we propose that acetyl-K177-METTL3 level, and/or the percentage of nuclear METTL3-positive tumor cells, may serve as prognostic factors predicting metastasis potential in breast cancer patients." (PMID 36289222, 2022). "However, in our study, we found that miR-532-5p is a tumor suppressor and targets METTL3 mRNA in breast cancer cells." (PMID 36077054, 2022). "There is also evidence shows that METTL3 can accelerate cell proliferation in breast cancer via inhibiting tumor suppressor let-7 g, and METTL3 could increase HBXIP expression to form a positive feedback loop of HBXIP/let-7 g/METTL3/HBXIP." (PMID 36058919, 2022). "Here, we have have found that METTL3 was overexpressed in docetaxel resistant breast cancer cells; besides, METTL3 could positively mediate docetaxel resistance of TNBC." (PMID 36202872, 2022). "Furthermore, we found that METTL3 regulated m6A levels in docetaxel-resistant breast cancer cells by regulating the expression of LINC00662." (PMID 36202872, 2022). "In addition, breast cancer tissue microarray was used to analyze the correlation between PD-L1 and METTL3 or IGF2BP3 expression." (PMID 35197058, 2022). "METTL3 was also demonstrated to be related with a poor survival rate in breast cancer." (PMID 35721510, 2022). "Our results suggested that PD-L1 could be a key mediator of METTL3/IGF2BP3-induced tumor immune surveillance in breast cancer cells." (PMID 35197058, 2022). "Additionally, we used the tissue microarray of breast cancer and found that METTL3, IGF2BP3, and PD-L1 were positively correlated by IHC staining." (PMID 35197058, 2022). "The authors identify an acetylation-mediated regulation of METTL3 subcellular localization and compartment-specific functions, a process that is fine-tuned by anti-inflammatory and pro-inflammatory signals, which ultimately determine breast cancer metastasis." (PMID 36289222, 2022). "Our study identifies an acetylation-dependent regulatory mechanism determining the subcellular localization of METTL3, which may provide mechanistic clues for developing therapeutic strategies to combat breast cancer metastasis." (PMID 36289222, 2022). "Taken together, we hypothesized that METTL3 expression was up-regulated to induced docetaxel resistance in breast cancer by activating the expression of LINC00662; moreover, LINC00662 sponged miR-186-5p to further increase the expression of METTL3." (PMID 36202872, 2022).
breast cancer (continued). "However, METTL3 is an oncogene in most tumors, although it has both carcinogenic and tumor-suppressing effects in colorectal cancer, breast cancer, prostate cancer, cervical cancer, and other cancers." (PMID 35945641, 2022). "However, few studies have also provided the converse findings regarding METTL3 expression and its tumor-suppressing role in endometrial and breast cancer." (PMID 35574388, 2022). "We transfected plasmid expressing wild-type ADAR1-p150 protein and plasmid expressing mutant type ADAR1-p150 (▲ E/A) protein, an RNA-editing inactive form of ADAR1 in which glutamate was changed to alanine, into breast cancer cell lines, respectively, to detect METTL3 mRNA levels." (PMID 36077054, 2022). "However, details about how METTL3 regulates YTHDF1-recognized ARHGAP5 to promote breast cancer progression need to be investigated in the future." (PMID 36077054, 2022). "In summary, our findings revealed the novel molecular pathway ADAR1/METTL3/ARHGAP5 connecting ADAR1, METTL3 and YTHDF1, which may indicate ADAR1 or METTL3 as prognostic and therapeutical targets for the treatment of breast cancer." (PMID 36077054, 2022). "Bcl-2 transcripts are upregulated following METTL3 methylation, indicating that METTL3 may promote breast cancer proliferation by regulating apoptosis." (PMID 36008936, 2022). "Furthermore, in breast cancer cells, METTL3 was found to participate in a feedback loop with HBXIP, a co-factor of anti-apoptotic protein SURVIVIN, wherein HBXIP up-regulated METTL3 expression by suppressing METTL3 inhibitor let-7g, an miRNA." (PMID 35350378, 2022). "In this study, we found that metformin could reduce the m6A level via decreasing METTL3 expression in breast cancer." (PMID 33431790, 2021). "METTL3 could promote breast cancer cell proliferation by regulating the p21 expression by an m6A-dependent manner." (PMID 33431790, 2021). "Moreover, the expression of METTL3 and circMETTL3 are positively correlated in breast cancer tissues." (PMID 33867838, 2021). "By analyzing transcriptome sequencings for MCF-7 cells treated with metformin and METTL3 knockdown SUM-1315 cells, we found that p21 might be the main target of METTL3 in breast cancer proliferation inhibitory effect of metformin." (PMID 33431790, 2021). "In addition, breast cancer and normal tissues were used to determine the role of METTL3 in breast cancer." (PMID 33431790, 2021). "In breast cancer, the expressions of METTL3, METTL14, KIAA1429, and FTO are upregulated." (PMID 34858499, 2021). "In the present study, we found that metformin could reduce the m6A level via decreasing METTL3 expression mediated by miR-483-3p in breast cancer." (PMID 33431790, 2021). "For instance, knockout of METTL3 may reduce the m6A modification level of specific transcripts which results in the inactivation of LncRNA X chromosome, whereas METTL3 was up‐regulated by LncRNA‐HBXIP which was highly expressed in breast cancer." (PMID 33934391, 2021). "Taken together, metformin could reduce the m6A level via decreasing METTL3 expression mediated by miR-483-3p in breast cancer." (PMID 33431790, 2021). "The half-life of p21 mRNA increased after METTL3 knockdown and decreased after METTL3 overexpression, suggesting that METTL3 could decrease p21 mRNA stability in breast cancer cells." (PMID 33431790, 2021). "Furthermore, using Kaplan–Meier analysis, we also found that breast cancer patients with higher expression of METTL3 had a tendency of worse prognosis and shorter disease-free survival, compared with those with lower expression of METTL3." (PMID 33431790, 2021). "Recent studies have shown that METTL3 is highly expressed in breast cancer tissue compared to normal tissue and that silencing METTL3 could lead to a decrease in proliferation, increased apoptosis, and thereby inhibit tumor growth in vivo and in vitro." (PMID 33376192, 2021). "In breast cancer, miRNA let-7 g downregulates the expression of METTL3 by targeting its 3’UTR." (PMID 34315512, 2021).